LXN (latexin)
Diseases named in the same sentence as LXN in open-access papers (continued):
Sharing a sentence is not in itself a finding about the gene and the disease.
atherosclerosis (continued). "LXN-deficient macrophages enhance cholesterol efflux by activating the STAT3/ATP-binding cassette transporter pathway, thus inhibiting the formation of foam cells and atherosclerosis." (PMID 39424784, 2024). "LXN deficiency stimulates the JAK1/STAT3/ABC transporter pathway, thereby enhancing the anti-inflammatory and anti-oxidant phenotype, cholesterol efflux, subsequently minimizing foam cell formation and atherosclerosis." (PMID 39424784, 2024). "Given our findings that LXN is enriched in plaques and colocalizes with macrophages in atherosclerotic lesions, we further determined whether LXN expression in macrophages regulates atherosclerosis in ApoE-/- mice." (PMID 39424784, 2024). "Bone marrow transplantation (BMT) experimentation was carried out to determine whether macrophage LXN regulates atherosclerosis." (PMID 39424784, 2024). "In this study, we further show that LXN is enriched in atherosclerotic plaques with the infiltration of macrophages in the tunica intima during atherosclerosis, therefore thus, suggesting the physiological role of macrophage-derived LXN in atherosclerotic plaque formation." (PMID 39424784, 2024). "Because macrophages play a key role in atherosclerosis, we speculate that LXN plays critical roles in atherosclerosis." (PMID 39424784, 2024). "LXN is a negative regulator of the macrophage anti-inflammatory phenotype and cholesterol efflux; thus, LXN inhibition may play a braking role in the formation of foam cell and atherosclerosis." (PMID 39424784, 2024). "Finally, we addressed whether exogenous changes in LXN expression can have therapeutic effects in atherosclerosis." (PMID 39424784, 2024). "Therefore, our study provides the experimental evidence that LXN targeted delivery could intervene atherosclerosis, which may open new therapeutic strategies for preventing atherosclerosis and cardiovascular disease." (PMID 39424784, 2024). "In summary, our study provides new clues for the role of LXN in the pathological regulation of atherosclerosis, and determines that LXN is a target for preventing atherosclerosis, which may be a potential new anti-atherosclerosis therapeutic target." (PMID 39424784, 2024). "Together, our data demonstrate that LXN ablation upregulates the expression of ABCA1 and ABCG1 in macrophages in vitro or atherosclerosis in vivo." (PMID 39424784, 2024). "To this end, we constructed a global LXN-deficient mice, and hybridized it with ApoE-/- mice to generate LXN/ApoE double-knockout mice, and then fed HFD for 12 weeks to induce atherosclerosis." (PMID 39424784, 2024). "Thus, LXN may be a new therapeutic target for anti-atherosclerosis." (PMID 39424784, 2024). "The cross-sectional analysis of the aortic root showed that the absence of LXN significantly decreased lesion area, indicating that deletion of LXN attenuates the progression of atherosclerosis." (PMID 39424784, 2024). "LXN is abundant in macrophages and plays critical roles in inflammation, however, the role of LXN in atherosclerosis has not been clarified." (PMID 39424784, 2024).
coronary artery disease (2 papers, 2024). "We previously reported that LXN in endothelial cells is critical for vascular homeostasis, and plasma LXN level is elevated in patient with coronary heart disease." (PMID 39424784, 2024). "Interestingly, LXN level was found to be elevated in blood plasma of coronary artery disease patients, indicating plasma LXN as a potential biomarker of cardiovascular disease." (PMID 39202445, 2024).
Hepatic steatosis (2 papers, 2009 to 2022). Steatosis is a term used to denote lipid accumulation within hepatocytes. "Importantly, we reveal that LXN deficiency in mice improves obesity-associated liver steatosis, glucose tolerance and insulin resistance, indicating the potential benefits of LXN deficiency in the diet-induced pathogenesis of obesity and obesity-associated metabolic syndrome." (PMID 35210404, 2022). "We found that mice deficient in LXN showed resistance against high-fat diet (HFD)-induced obesity, glucose tolerance, insulin tolerance and hepatic steatosis." (PMID 35210404, 2022). "Histologic analysis of the liver from WT mice on HFD showed macrovesicular hepatic steatosis as evidenced by a fatty liver populated with abundant large vacuolar lipid droplets, whereas the liver of LXN−/− mice had few lipid droplets, as determined by H&E and Oil Red O staining." (PMID 35210404, 2022).
neuroblastoma (2 papers, 2011 to 2023). Neuroblastoma (NB) is the most common solid, extracranial childhood tumor. "RecombinantrAAV2 (rAAV2-hSyn-latexin-EGFP) mediated enhancement of latexin expression wasconfirmed in human neuroblastoma cells (SH-SY5Y)." (PMID 21572518, 2011).
osteoarthritis (2 papers, 2023). A noninflammatory degenerative joint disease occurring chiefly in older persons, characterized by degeneration of the articular cartilage, hypertrophy of bone at the margins and changes in the synovial membrane. "For example, circ_0002715 promotes the development of osteoarthritis through regulating LXN by sponging miR-127-5p." (PMID 37491357, 2023).
prostate carcinoma (2 papers, 2019 to 2024). A carcinoma that arises from epithelial cells of the prostate gland. "Therefore, we aimed to further characterise the expression patterns and define a molecular function for LXN in the normal and malignant prostate in order to determine how potential loss of LXN signalling in advanced prostate cancer might be exploited as a rational therapeutic target in CaP." (PMID 30914656, 2019). "In order to understand the wider relevance of this finding, we interrogated a publicly available dataset and found LXN mRNA levels to be significantly downregulated in metastatic prostate cancer specimens when compared to normal prostate tissue 23,24." (PMID 30914656, 2019). "Antitumour proteins such as latexin, glutathione S-transferase P, Rho GDP-dissociation inhibitor 1, and serpin B5 were reduced in their expression in PC3 prostate cancer cells, in agreement with the previous studies." (PMID 38249992, 2024).
bladder cancer (1 paper, 2019). "Interestingly, we found LXN protein to be extremely stable with a half-life exceeding 24 hours (a proteomic study in a bladder cancer cell line suggested 48 hour half-life)." (PMID 30914656, 2019).
colitis (1 paper, 2020). Inflammation of the colon. "We found that LXN deficiency accelerates the process of dextran sulfate sodium (DSS)-induced colitis in mice." (PMID 32555320, 2020). "We reveal that LXN deficiency leads to the severity of mice colitis induced by DSS, and ectopic LXN attenuates inflammatory response by inhibiting the ubiquitination and degradation of IκBα." (PMID 32555320, 2020). "LXN deficiency leads to the severity of colitis in DSS-induced mice, and LXN is required for the therapeutic effect of retinoic acid on colitis." (PMID 32555320, 2020). "Thus, our findings provided a novel mechanism underlying LXN modulates colitis via HECTD1/Rps3/NF-κB pathway and significant implications for the development of novel strategies for the treatment of colitis by targeting LXN." (PMID 32555320, 2020). "We further examined the production of inflammatory cytokines in serum and colon tissues from WT and LXN−/− mice during DSS-induced colitis." (PMID 32555320, 2020). "In this study, we believe that this model has been able to demonstrate the important role of LXN in the development of colitis." (PMID 32555320, 2020). "Our study provides a novel mechanism by which LXN modulates colitis, suggesting LXN is a potential target for IBD treatment." (PMID 32555320, 2020). "Compared with LXN−/− mice, RA has better therapeutic effect on WT DSS colitis mice, further demonstrating that LXN mediates the anti-inflammatory process of RA." (PMID 32555320, 2020). "The data indicate that LXN is required for the therapeutic effect of retinoic acid on DSS colitis in mice." (PMID 32555320, 2020). "Our findings highlight a correlation between LXN and colitis via HECTD1/Rps3/IκBα pathway." (PMID 32555320, 2020). "In summary, this study shows that LXN is a critical regulator in colitis." (PMID 32555320, 2020). "We found that the levels of TNF-α, IL-1β, and IL-6 were significantly increased, however, the production of IL-12 was remarkably decreased in LXN−/− mice during DSS-induced colitis, suggesting TNF-α, IL-1β, IL-6 and IL-12 involved in DSS-induced colitis in LXN−/− mice." (PMID 32555320, 2020). "Thus, we provide a novel mechanism by which LXN modulates colitis and significant implications for the development of novel strategies for the treatment of IBD by targeting LXN." (PMID 32555320, 2020). "We hypothesize that LXN may play a role in the treatment of colitis with retinoic acid." (PMID 32555320, 2020). "Therefore, we speculate whether LXN mediates the anti-inflammatory effect of RA in colitis." (PMID 32555320, 2020). "RA treatment significantly decreased the levels of TNF-α, IL-6, and IL-1β in colon tissue in WT mice during DSS-induced colitis, but the effect is not obvious in LXN−/− mice." (PMID 32555320, 2020). "However, treatment with RA resulted in significant amelioration of colitis in WT mice, but not in LXN−/− mice, as shown by an increase body weight, colon length, improvement in splenomegaly and reduced rectal bleeding (data not shown)." (PMID 32555320, 2020). "However, the functional roles of LXN in inflammatory are less well understood, and no data are available regarding the role of LXN in colitis." (PMID 32555320, 2020).
colorectal tumor (1 paper, 2022). "We also observed a significantly increased of PD-L2+ cells in the colorectal tumor tissues in AOM/DSS-induced mice received LXN−/−BM." (PMID 36323670, 2022). "We found that B220+ cell and CD3+ T cell were significantly reduced in the colorectal tumor of LXN−/− mice compared to WT mice." (PMID 36323670, 2022). "However, F4/80+CD11b+ macrophages, particularly PD-L2+ macrophages (CD45+CD11b+PD-L2+) infiltrated in the colorectal tumor of LXN−/− mice was significantly higher than that in WT mice." (PMID 36323670, 2022).
dilatation (1 paper, 2021). "Of these, IGFBP-2, PSG4, and LXN levels in plasma were independent of cervical dilatation." (PMID 33857242, 2021).
endometriosis (1 paper, 2024). The growth of functional endometrial tissue in anatomic sites outside the uterine body. "Our study has expanded knowledge on the expression and possible functions of the relatively unexplored LXN gene in the context of endometrium and endometriosis." (PMID 39202445, 2024). "In conclusion, our results showed that LXN can be involved in the pathogenesis of endometriosis by regulating the proliferation and migration activity of endometriotic stromal cells." (PMID 39202445, 2024). "The aim of this study was to investigate the expression of new potential candidate gene latexin (LXN), an inhibitor of carboxypeptidases, in endometrium and endometriotic lesions to elucidate its possible role in endometriosis development." (PMID 39202445, 2024). "In this study, we examined the expression pattern of LXN throughout the menstrual cycle in the endometrium of women with and without endometriosis and explored its possible roles in the pathogenesis of endometriosis using LXN-silenced endometrial stromal cells." (PMID 39202445, 2024). "Thus, we cannot dismiss the possibility that LXN plasma levels are altered in endometriosis; however, the LC-MS/MS method we employed is unsuitable for detecting its presence in plasma." (PMID 39202445, 2024). "LXN expression is elevated in endometriotic lesions; however, it is unclear whether the high LXN level plays a crucial role in the development of endometriosis or if its expression is increased due to the local effects from peritoneal environment following the formation of endometriotic lesions." (PMID 39202445, 2024). "As LXN is naturally highly expressed in stromal cells, we transfected the cells with LXN-siRNA to suppress the LXN gene expression and determined whether reducing its level affects cell migration and viability, i.e., functions that are important for endometriosis pathophysiology." (PMID 39202445, 2024). "We found that the mRNA level of LXN was similar in the endometrial samples from women with and without endometriosis and changed throughout the menstrual cycle, being the highest in the LS phase." (PMID 39202445, 2024). "However, there is no data on the dynamics of LXN expression in endometrium or its possible role in endometriosis." (PMID 39202445, 2024). "However, there was no data about LXN expression neither in endometrium throughout the menstrual cycle nor in endometriosis." (PMID 39202445, 2024). "Consequently, although LXN has been suggested as a blood-based cardiovascular disease biomarker, it may not be a feasible non-invasive biomarker candidate for endometriosis." (PMID 39202445, 2024).
Insulin resistance (1 paper, 2022). Increased resistance towards insulin, that is, diminished effectiveness of insulin in reducing blood glucose levels. "Since LXN deficiency can alleviate obesity induced by high-fat diet, we want to know whether LXN deficiency can also improve obesity complications, such as hepatosteatosis and insulin resistance." (PMID 35210404, 2022).
metastatic disease (1 paper, 2019). "Our new data describes LXN as a predominantly luminal protein that is downregulated in high grade primary and metastatic disease." (PMID 30914656, 2019).
metastatic prostate carcinoma (1 paper, 2019). A carcinoma that arises from the prostate gland and has spread to other anatomic sites. "Finally, we found that metastatic prostate cancers also showed a striking down-regulation of LXN compared to non-malignant specimens." (PMID 30914656, 2019).
Obesity (1 paper, 2022). Accumulation of substantial excess body fat. "We show that LXN-deficient mice have reduced HFD-induced obesity and improved glucose tolerance and insulin sensitivity." (PMID 35210404, 2022). "Collectively, these data provided evidence suggesting that LXN-deficient mice are resistant to HFD-induced obesity." (PMID 35210404, 2022). "We observed that loss of LXN ameliorated HFD-induced obesity in mice and inhibited adipogenesis of adipocytes in vitro, which prompted us to ask whether LXN deletion affects the expression of PPARɤ." (PMID 35210404, 2022). "Collectively, our data provide evidence that LXN is a key positive regulator of adipocyte differentiation, and therapeutics targeting LXN could be effective in preventing obesity and its associated disorders in clinical settings." (PMID 35210404, 2022). "We found that LXN in fat tissues was continuous increased during the development of diet-induced obesity." (PMID 35210404, 2022). "The aim of this study was to evaluate the role of LXN on adipocyte differentiation, as well as its effects on high fat-induced obesity and metabolic disorders." (PMID 35210404, 2022). "In the present study, we examined the roles of LXN in adipocyte differentiation and obesity in mice." (PMID 35210404, 2022). "We found that LXN is upregulated in adipose tissue of mice by body adiposity, and mice deficient in LXN were protected from HFD-induced obesity." (PMID 35210404, 2022). "Here, we investigated the role of LXN in adipocytes differentiation and metabolic disorders in mice with diet-induced obesity." (PMID 35210404, 2022). "We fed wild-type (WT) and LXN−/−mice with high-fat diet (HFD) to study the effects of LXN on obesity and related metabolic functions." (PMID 35210404, 2022). "When C57/BL6 mice were induced to develop obesity by feeding with high-fat diet (HFD), the expression of LXN in adipose tissues was significantly upregulated after 8-23 weeks of HFD feeding." (PMID 35210404, 2022).
pancreatic cancer (1 paper, 2014). "Latexin (Lxn) is a negative regulator of stem cell proliferation and we investigate the effects of Lxn on CD133+ pancreatic cancer stem-like cells." (PMID 25551472, 2014).
tumor (23 papers, 2011 to 2025). "Latexin has been suggested to function as a potential tumor suppressor which reduces the risk of old stem cells transforming into cancer stem cells." (PMID 21466706, 2011). "Collectively, our data preliminarily demonstrated that LXN deficiency remodeled the pro-tumor microenvironment of mice by promoting the infiltration of M2-macrophages and attenuating T cells in tumor tissue, thus promoting the growth of subcutaneous tumor." (PMID 36323670, 2022). "RNA-seq analysis of bone marrow derived macrophages (BMDMs) showed that LXN-deficient BMDMs had enhanced PD-L2 expression and tendency to polarize into M2 phenotype, which contributes to the immune escape of cancer cells by attenuating the function of T cells in tumor microenvironment." (PMID 36323670, 2022). "Therefore, loss of LXN expression by tumour cells might be a novel mechanism of tumour immune cell evasion, for instance by blocking maturation of B and T cells." (PMID 30914656, 2019). "Collectively, we define a critical role of LXN/JAK1/STAT3 signal in macrophage and highlights the potential role of LXN in tumor immune-escape by regulating macrophage polarization, as well as the expression of immune checkpoint PD-L2." (PMID 36323670, 2022). "To evaluate the effect of LXN-deletion on mice immune system, we examined the cancer cell growth in littermate wild-type (WT) and LXN−/− mice (KO) by subcutaneous tumor model." (PMID 36323670, 2022). "We and other groups have reported that LXN plays important roles in the inhibition of stem cell proliferation and tumor growth." (PMID 36323670, 2022). "Here, we provide evidence that LXN is involved in tumor immunomodulation by regulating macrophage PD-L2 expression." (PMID 36323670, 2022). "In conclusion, the present study revealed the crucial role of LXN in tumor tumorigenesis from an immunological perspective, and its ability to regulate tumor microenvironment through modulating JAK1/STAT3/PD-L2 axis in macrophages." (PMID 36323670, 2022). "Consistently, the tumor loads and tumor size were higher in mice received LXN−/−BM than in mice received WT BM." (PMID 36323670, 2022). "LXN has also been shown to be involved in the inflammatory response with inhibition of tumor growth and colony formation." (PMID 33218162, 2020). "Our findings therefore highlight the importance of future study into the effects of LXN on immune cell infiltration and function within the tumour micro-environment." (PMID 30914656, 2019). "LXN mainly functions as a potential tumor suppressor and reduces the stem cells transformation into cancer stem cell." (PMID 28174608, 2017). "Recently, the latexin (Lxn) gene was identified as a potential tumor suppressor in several types of solid tumors and lymphoma, and Lxn expression was found to be absent or downregulated in leukemic cells." (PMID 25341047, 2014). "5-aza-2′-deoxycytodine treatment and bisulfite sequencing revealed hypermethylation of latexin promoter in tumor cells." (PMID 23028717, 2012). "Consistent with its tumor suppressor potential, ectopic expression of latexin in C39-8 cells increased expression levels of Maspin or WFDC1 by more than 2 or 3 fold separately." (PMID 21466706, 2011). "Conversely, BGC823 cells transfected with antisense LXN gene exhibited enhanced tumor growth and colony formation." (PMID 21466706, 2011). "MGC803 and BGC823 cells were therefore used to evaluate the effect of latexin expression on tumor cell growth." (PMID 21466706, 2011). "Taken together, these results strongly suggest that latexin acts as an inhibitor of tumor cell growth and tumorigenicity." (PMID 21466706, 2011). "Recent studies also highlighted that the PIWIL2 protein works in combination with piR-932 influencing the biological behavior of BCSCs through the methylation of Latexin (LXN) gene, coding for a tumor suppressor protein which reduces the risk of old stem cells transforming into cancer stem cells." (PMID 40951838, 2025).